IFNG (interferon gamma)
Diseases named in the same sentence as IFNG in open-access papers (continued):
Sharing a sentence is not in itself a finding about the gene and the disease.
infection (continued). "DCSR4, bearing solely the D322N Alr mutation, was attenuated during infection of naive and of interferon-gamma-activated human macrophages, compared with the parent strain." (PMID 31519879, 2019). "Susceptible mice can resolve a primary infection with attenuated Salmonella strains which requires a functioning immune system that can develop a T-bet-dependent Th1 cell response and IFNγ production to activate infected macrophages." (PMID 32038650, 2019). "In contrast, Tg infection of IFNγ‐stimulated human foreskin fibroblasts causes an unspecified form of cell death." (PMID 31268602, 2019). "On the other hand, IFNγ−/− mice, from which γδT cells were eliminated, showed a considerable increase in susceptibility to the infection by B. abortus." (PMID 31481953, 2019). "This increase in T cell survival and IFNγ makes infected mice susceptible to infection by decreasing tolerance." (PMID 30258448, 2018). "Infectious challenge of IFNγ-treated CD4-depleted FVB mice with Pneumocystis demonstrated that they were highly susceptible to infection." (PMID 30283457, 2018). "Important is that when the role of T cells and IFNγ are considered within a trypanosomosis context, IL-10 was shown to be the main counter regulator of infection-associated inflammation in both T. brucei and T. congolense models." (PMID 30333827, 2018). "Here, we show a neutralizing antibody response, dependent on CD4+ T cells and IFNγ signaling, which we detected during the first week of infection and is associated with reduced viral load in the brain, prevention of rapid disease onset and survival." (PMID 30087337, 2018). "The balance between the protective T-helper (Th) 1 cellular response, which was associated with the cytokine interferon-gamma (IFN-γ), and the humoral immune response mediated by Th2 lymphocytes determines the clinical manifestation of the infection." (PMID 29547503, 2018). "Since infections often are associated with exacerbation of COPD symptoms we looked at the modulation of IFNγ, and the 10 analytes which correlated most closely with it in sputum either pre-, during or post-exacerbation." (PMID 28830544, 2017). "Second, C57BL/6 IFNγ-/- mice show enhanced susceptibility and lethality in the infection with R. australis." (PMID 28222146, 2017). "Neutralization of either IFNγ or TNFα was associated with reduced nitric oxide (NO) production, led to uncontrolled bacterial growth and was fatal for C3H/HeN mice upon infection with a normally sublethal dose of R. conorii." (PMID 28222146, 2017). "The dominance of a Th2 response in patients who are at higher risk of infection was confirmed by the significantly lower Th1/Th2 ratio as represented by IFNγ/IL4 levels seen on univariate analysis." (PMID 29051761, 2017). "For example, C57BL/6 Perforin-/- mice showed a higher susceptibility and lethality upon infection with R. australis compared to C57BL/6 IFNγ-/- mice." (PMID 28222146, 2017). "Host immune parameters such as the magnitude of interferon gamma and interleukin-10 responses have been implicated in the outcome of infection." (PMID 28934262, 2017). "IFNγ serum levels were significantly reduced upon NK cell depletion by antibody, and the mice showed enhanced susceptibility to the infection with R. conorii." (PMID 28770333, 2017). "Interferon gamma (IFN-γ) has been implicated as essential for controlling the replication of F. tularensis during the initial infection." (PMID 28611741, 2017). "The enhanced susceptibility of C3H/HeN mice to the infection with R. conorii compared to C57BL/6 mice has been connected to the reduced ability of DCs to induce IFNγ-producing CD4+ T cells." (PMID 28770333, 2017). "Nevertheless, IFNγ-pulsed HIF-1α-deficient Ly6Chi/int monocytes were slightly more resistant to infection than wild type inflammatory monocytes." (PMID 28892492, 2017).
infection (continued). "This increased infection was associated with lower levels of IFNα, IFNλ and IFNγ in the BAL fluid and lungs at seven dpi in PVM-infected RAGE deficient mice." (PMID 28099113, 2017). "Induction and proliferation of CD4+ T-cells and production of interferon-gamma (IFNγ) have been implicated in successful resolution of infection in animal models and human infections." (PMID 28851925, 2017). "Infection was associated with particularly marked increases in expression of IFNG (FC: 7.12, p-value: 1.32E-42) and IL22 (FC: 6.49, p-value: 1.6E-23)." (PMID 28966918, 2017). "C57BL/6 Perforin−/− mice that lack the cytotoxic potential show a higher susceptibility and lethality upon infection with R. australis compared to C57BL/6 IFNγ−/− mice, although being much less susceptible than C57BL/6 MHCI−/− that lack CD8+ T cells at all." (PMID 28770333, 2017). "Infection with H. pylori wt caused a 13.1-fold and 2.2-fold increase in IFNγ and IL-17 A expression in the gastric mucosa, respectively." (PMID 29057967, 2017). "The weight loss of surviving animals of this group was less pronounced and peaked on day 16 post infection (-5.44±2.59%) while isotype-treated surviving CD4+IFNγ-/- T cell recipients still showed weight loss of -16.45±1.55% at this point in time." (PMID 28222146, 2017). "IFNγ is linked to moDC development in other models and plasma IFNγ levels were decreased in MyD88-/- compared to WT mice after LCMV-Cl13 infection." (PMID 26808628, 2016). "To verify this in our infection model, we infected IFNγ- and IL-18-deficient mice for 72h with S.Tm, a time point when the pathogen has spread from the mucosal tissue to systemic organs." (PMID 27341123, 2016). "At the beginning of infection (first 4 weeks), parasite replication is associated with the immune cell inability to produce IFNγ and IL2 (macrophage-activating cytokines), whereas production of IL4 or IL5 is conserved." (PMID 26969511, 2016). "We analysed the production of typical T-cell associated cytokines such as IL-6, IL-17 and IFNγ at the primary site of infection in the abscessed tissue of the thigh muscle." (PMID 27103319, 2016). "At 18 hr post-infection, prior to the onset of viral DNA replication, IFNα or IFNγ decreased the association of GABP with the E1A enhancer in vivo 3- and 2.5-fold, respectively." (PMID 26809031, 2016). "In murine ehrlichiosis, IFNγ is required for BM-resident MΦ maintenance, and is also essential for the infection-dependent loss of HSCs." (PMID 27621733, 2016). "It has been described that knockout mice for IFNG are highly susceptible to infection due to defective macrophage activation and nitric oxide production." (PMID 27027876, 2016). "Mice inoculated with low doses showed a minimal infection associated with a Th1 response (IFNγ and NO production in spleen), whereas high doses led to high parasite burden in spleen and lymph nodes as well as to a Th2 response." (PMID 26969511, 2016). "Both IFNα and IFNγ impede the association of the transactivator GABP with the E1A enhancer region during the early phase of infection." (PMID 26809031, 2016). "Over the subsequent 10 years, several reports have documented the association of AAbs to IFNγ with intracellular infections in otherwise healthy, immune competent individuals." (PMID 31557985, 2016). "As expected, TNFα, IL6 and IFNγ cytokines were enhanced by the infection, which have been associated with the progression of hepatic and cardiac injury." (PMID 25668433, 2015). "Mice deficient in IL-18 quickly succumbed to the infection but administration of IFNγ rescued their survival." (PMID 25768794, 2015). "Using an in vivo-like in vitro mucosal surface, we identified that infection per se, as well as TNFα, individually and more severely in combination with IFNγ, caused the same effects as seen in vivo." (PMID 26481427, 2015).
infection (continued). "In conclusion we have demonstrated that HPIV3 effectively infects upper airway epithelial cells and the infection is associated with induction of interferon gamma." (PMID 25722655, 2015). "We examined the roles of IFNγ, TNFα and LTα in brain microvessel cross-presentation during PbA infection by comparing mice deficient in each cytokine with wild type (WT) C57BL/6J mice." (PMID 26046849, 2015). "Infection per se, and also in combination with TNFα and IFNγ, caused a reduction in mitochondrial phosphorylation capacity." (PMID 26481427, 2015). "In conclusion, infection with this A/E pathogen induces mitochondrial dysfunction, which is largely caused by IFNγ and TNFα synergistically compromising complex I and IV levels and activity, via NO generation." (PMID 26481427, 2015). "Our results suggest that NO generation caused by infection-induced TNFα and IFNγ was the main cause of mitochondrial dysfunction." (PMID 26481427, 2015). "T helper cells are crucial to survival following experimental intravenous S. aureus inoculation, and a protective role for Th1 cells is suggested by the finding that IFNγ-deficient mice are hypersusceptible to such infection." (PMID 26539822, 2015). "IL-17 concentrations were closely correlated with IFNγ levels, and associated with rate of clearance of infection and survival." (PMID 25853653, 2015). "The TLR9 deficient mouse showed reduced CCL7 production, and restoration of CCL7 over the first week of infection relieved the associated suppression of interferon gamma and recruited DC numbers." (PMID 25498576, 2015). "Infection by T. cruzi triggers a strong proinflammatory response, especially composed of IFNγ, a cytokine associated with infection control both systemically and in the heart tissue." (PMID 25695249, 2015). "Infection of lambs was associated with an increase in the expression of the IFNγ and IL22 genes which was evident from as early as 1 dpi with a further increase observed at 3 and 6 dpi." (PMID 25890354, 2015). "Our data show that primary infection induces significantly higher amounts of IFNγ in IL-1β and IL-1R deficient mice than in wild-type mice on day 14 post-inoculation." (PMID 25198773, 2014). "In wildtype cells, IFNγ-induction resulted in complete loss of the meront marker at 2 and 5 days after infection, while in the Irgm1/Irgm3−/− double knock-out cells IFNγ-induction caused no inhibition of meront growth." (PMID 25356593, 2014). "Interferon-γ has been shown to protect mice from influenza virus if administrated at an early stage of infection, and genetic variation within the IFNG gene has been linked to SARS in humans." (PMID 24902603, 2014). "Increased levels of IFNγ in serum have been associated with infections and adverse events linked to vaccination." (PMID 24498105, 2014). "A time series of 0.5 to 24 hours post infection showed continuous IFNγ-dependent loss of E. cuniculi meronts (determined by counting of 6G2-positive meronts per host nuclei)." (PMID 25356593, 2014). "Transcript levels of other Lyme arthritis-associated genes (IFNγ, Cxcl10, TNFα) were very similar between the two strains, and showed a peak in expression at 2 weeks post-infection, followed by resolution at 4 weeks." (PMID 24967703, 2014). "Induction of a strong serum IgG and splenic cell-mediated response, dominated by pro-inflammatory cytokines IFNγ, TNFα, IL-17, was associated with the protection against infection." (PMID 23613984, 2013). "Systemic pro-inflammatory cell-mediated responses were also associated with the enhanced resolution of infection, possibly due to the synergistic effect of IFNγ, TNFα and IL-17." (PMID 23613984, 2013). "Alternatively, another group showed adoptive transfer of IFNγ-deficient T cells protected mice from lethal infection as well as wild-type cells." (PMID 24153060, 2013).
infection (continued). "The generation of interferon-gamma (IFN-γ) by MHC class II activated CD4+ T helper cells play a substantial contribution in the control of infections such as caused by Mycobacterium tuberculosis." (PMID 24304645, 2013). "Infection experiments with mice deficient for various genes proved the importance of interferon (IFN)γ; IFNγ-deficient mice die in the acute phase during the first week of infection." (PMID 24324375, 2013). "The ESAT-6 and CFP10 proteins function in inducing interferon gamma (IFNγ) from memory effector cells upon infection with pathogenic mycobacteria." (PMID 23166708, 2012). "RSV disease and early age of infection are independently associated with a Th2-type cytokine response, hallmarked by increased IL-4 and/or reduced IFNγ production." (PMID 22792355, 2012). "Infection was also associated with emergence of a population of splenic CD3ε+CD4+ T cells capable of producing both IFNγ and IL-10." (PMID 22911108, 2012). "As observed in the single infection, the early peak of IFNγ (having activity >1) was caused by an initial host-mediated inflammatory response, as an immediate-type hypersensitivity reaction of the tissue to the establishment of infective larvae." (PMID 22253585, 2012). "Enhanced IFNγ-responses by C. pneumoniae-specific CD4+ T-cells in TLR2/4 double-deficient mice are best explained by an impaired infection-associated expansion of CD4+CD25+Foxp3+ regulatory T-cells." (PMID 22096480, 2011). "The cytokine profile in reactivating Tm-TNF mice reported here contrasts to that observed in de novo infected Tm-TNF mice with respect to pulmonary IFNγ AND IL-10 concentrations during late stage infection despite similar observed susceptible phenotypes." (PMID 22132068, 2011). "In association, previous studies have shown the importance of IFNγ-producing CD4+ T-cells in increasing resistance of RAG-1/IFNγ-double-deficient mice against an infection with C. pneumoniae." (PMID 22096480, 2011). "We recently showed that the development of protection against infection with P. falciparum in human volunteers is associated with the induction of IFNγ+IL-2+ double-positive (polyfunctional) EM T cells in response to PfRBC." (PMID 22144890, 2011). "Infection of IL-1 receptor type 1 knockout mice with MTB is associated with lower production of IFNγ, defective granuloma formation, and lower survival." (PMID 21603213, 2011). "Previous studies have shown that DCs from L. major susceptible mice produced low quantities of IL-1α and IFNγ in response to LPS and this was thought to be responsible for different outcomes after infection by the parasite." (PMID 21857913, 2011). "TLR2/4 double deficient mice lost considerably more weight at day 12 post infection than wild type mice despite increased IFNγ levels." (PMID 22096480, 2011). "In agreement with the data presented here, infection of MyD88-deficient mice with Mycobacterium bovis BCG also triggered CD4+ T-cells to produce IFNγ." (PMID 22096480, 2011). "In vivo treatment with p60 increased serum IFNγ and reduced susceptibility of recipient mice to infection by the heterologous NK cell-sensitive bacterial pathogen, Francisella tularensis." (PMID 22072975, 2011). "Despite CD28-deficient animals being resistant to T. gondii infection, blockade of ICOS in vivo made these mice more susceptible to infection by reducing the proliferation and level of IFNγ production by T cells." (PMID 21687650, 2011). "In humans, IFNγ production and iNOS expression have also been directly associated with the resolution of infection." (PMID 21072232, 2010). "Consistently, experiments performed in our laboratory and elsewhere demonstrate that despite of severe impairment IL-12 production in MyD88−/− mice, IFNγ is still produced at 8 days post-infection, and yet, mice are highly susceptible to ME-49 infection." (PMID 20865117, 2010).
infection (continued). "Nevertheless, animals bearing UNC93B1 mutation succumbed to infection as a result of unchecked tachyzoite replication, similar to IFNγ−/− mice." (PMID 20865117, 2010). "This relatively benign course of infection is, however, drastically altered by disruption of genes encoding key components of the interferon-gamma (IFNγ)-response pathway." (PMID 19197351, 2009). "Transcript encoding the cytokine IFNγ was detected in mouse lung tissue at various time points in response to PVM infection." (PMID 19298652, 2009). "Early induction of T cell signaling genes during pathogenic infection supported a trend for Th1 cell differentiation and proliferation, cytotoxic T cell activity, and extensive IFNγ signaling." (PMID 19214219, 2009). "Here we elucidate the mechanisms underlying IFNγ/IRGs-induced immunity to C. trachomatis in murine cells, demonstrating a pivotal role for Irga6 in mediating host resistance to infection via the induction of autophagy." (PMID 19242543, 2009). "Infection with HTLV-1 was associated with higher spontaneous IFNγ release by CD4+ T cells, but only in HAM/TSP there was a marked increase in T cell proliferation." (PMID 18664281, 2008). "For instance, it was observed that IFNγ secreting CD4+ T cell responses developed earlier in patients with asymptomatic CMV infection than in patients with symptomatic infection and were associated with clearance of the virus." (PMID 19023425, 2008). "Here, we prospectively compared the accuracy of the whole blood interferon-gamma assay with that of the traditional TST in healthcare students thought to be at a low risk of infection with M tuberculosis." (PMID 17726533, 2007). "Indeed, IFNγ deficiency has been shown to induce a pronounced increase of susceptibility to infection." (PMID 40762872, 2025). "To reduce inflammation during PbA infection, we tested whether systemic loss of IFNγ would change the phenotype and persistence of responding OT-I T cells." (PMID 40163479, 2025). "The question is whether the intrOv’s delay in establishing a productive infection in the lower genital tract tissues is also caused by IFNγ+ILC3s." (PMID 40407332, 2025). "We hypothesize that this phenotype is caused by the inflammatory signature of PbA infection, but further investigations are necessary to identify specific causes beyond IFNγ." (PMID 40163479, 2025). "Our study of real-world primary SARS-CoV-2 infection, CHIM studies of primary infection and studies of breakthrough infections in vaccinated individuals all converge on the finding that a subset of expanding IFNγ-secreting or CD8+ T cells are associated with superior viral control." (PMID 40472803, 2025). "Thus, L. major-infected CXCR3-/- mice are more susceptible to infection due to a reduced number of CD4+T cells producing IFNγ in the lesion." (PMID 38709823, 2024). "This may suggest that cocaine induced changes in GM-CSF and interferon gamma could impact subsequent risk for HIV infection or infection outcomes in people with a history of chronic cocaine exposure." (PMID 38553542, 2024). "Infection-induced pro-inflammatory cytokines, namely IFNγ and TNFα, are associated with unstable plaques, which may then be dislodged, resulting in occlusion." (PMID 38675778, 2024). "However, other studies suggest this deficiency is only apparent early during infection, as IFNγ responses later in infection are equal or even greater in IL-27Rα KO mice." (PMID 38390338, 2024). "We found that Chlamydia decreases the expression of multiple components that are required for inducing gene expression by IFNγ, providing a possible mechanism by which Chlamydia trachomatis can attenuate the immune response in the female genital tract to cause long-term infections." (PMID 39194253, 2024). "Interestingly, we found that STAT1 deficiency resulted in increased susceptibility to infection compared to deficiency in IFNγ alone." (PMID 39440975, 2024).